EIF4B (eukaryotic translation initiation factor 4B)
Diseases named in the same sentence as EIF4B in open-access papers (continued):
Sharing a sentence is not in itself a finding about the gene and the disease.
epileptic seizures (1 paper, 2024). "Since eIF2a and eIF4B phosphorylation positively regulate BACE1 mRNA levels and PERK-mediated phosphorylation of eIF2a is induced in TLE, epileptic seizures might increase BACE1 mRNA levels via eIF2a phosphorylation." (PMID 39545066, 2024).
fibrosis (1 paper, 2023). the formation of excess fibrous connective tissue in an organ or tissue in a reparative or reactive process. "Mechanistically, Ltf interacts with CD74, which in turn represses the activation of mTORC1/S6K/eIF-4B axis to depress cardiac fibrosis after MI." (PMID 37351157, 2023). "Taken together, these data indicate that mTORC1/S6K/eIF-4B axis serves as the primary pathway involved in Ltf-mediated suppression of cardiac fibrosis after MI." (PMID 37351157, 2023). "We presented the first direct evidence that Ltf could attenuate adverse cardiac remodeling and improve cardiac function via inhibiting excessive cardiac fibrosis post-MI, mainly through suppressing the activation of mTORC1/S6K/eIF-4B axis in myofibroblasts." (PMID 37351157, 2023).
heart failure (1 paper, 2023). Inability of the heart to pump blood at an adequate rate to meet tissue metabolic requirements. "Targeting mTORC1/S6K/eIF-4B signaling pathway can alleviate cardiac remodeling and heart failure in response to pressure overload conditions and myocardial infarction 2,41." (PMID 37351157, 2023).
Hyperammonemia (1 paper, 2023). An increased concentration of ammonia in the blood. "Shared DAP that were increased at both 6 and 24 h of hyperammonemia included Eif4b, Map4, Arpc1b, Eif3b, S100a4, Smad4, and Hist1h2bb." (PMID 37101412, 2023).
hyperopia (1 paper, 2022). A refractive error in which rays of light entering the eye parallel to the optic axis are brought to a focus behind the retina, as a result of the eyeball being too short from front to back. "Also, a GNAS gene was associated with HM, TRAM1, CTNNB1, TENM3 and RUNX with myopia and/or refractive error, and EIF4B with low myopia/hyperopia in Europeans." (PMID 36685896, 2022).
myopia (1 paper, 2022). "Several targets of these miRNAs, e.g. GNAS, TRAM1, CTNNB1, EIF4B, TENM3 and RUNX were previously associated with myopia/HM/refractive error in Europeans in genome-wide association studies." (PMID 36685896, 2022).
osteoarthritis (1 paper, 2021). A noninflammatory degenerative joint disease occurring chiefly in older persons, characterized by degeneration of the articular cartilage, hypertrophy of bone at the margins and changes in the synovial membrane. "Among them, Ribosomal proteins were upregulated in the synovial membranes of female patients with Osteoarthritis, Carhsp1 can regulate the stability of TNF -α mRNA, they might be associated with RA, no other proteins, such as Wars, Yars, Bzw2, Mcts1 and Eif4b were reported in RA." (PMID 35006449, 2021).
sarcoma (1 paper, 2023). A usually aggressive malignant neoplasm of the soft tissue or bone. "Kaplan-Meier survival curves from the TCGA sarcoma dataset demonstrated that increased expression patients (cut-off by the median gene expression value) of EIF4B or YRDC had a lower 10-year overall survival rate." (PMID 36897170, 2023).
thyroid hypoplasia (1 paper, 2025). Thyroid hypoplasia is a form of thyroid dysgenesis characterized by incomplete development of the thyroid gland that results in primary congenital hypothyroidism, a permanent thyroid deficiency that is present from birth. "They identified a patient with biallelic variants of the eukaryotic translation initiation factor 4B (EIF4B) gene and thyroid hypoplasia." (PMID 41303336, 2025).
cancer (28 papers, 2015 to 2026). A tumor composed of atypical neoplastic, often pleomorphic cells that invade other tissues. "Although eIF4B has been implicated in regulating the growth and proliferation of cancer cells, the exact mechanisms are unclear." (PMID 39225047, 2024). "EIF4B has been shown to induce cell transformation, is considered an oncogene, and leads to further cancer risk." (PMID 38202644, 2023). "Various translation regulators such as eIF4B, ABCE1 and 4E-BP1, or ribosomal proteins, for example RPL29 or RPL9 which have been linked to malignant PCa and other cancers, were found in low abundance in VCaPER." (PMID 36348939, 2022). "Eukaryotic Translation Initiation Factor 4B (EIF4B) regulates cancer cell proliferation and has been reported as a potential target for developing anticancer therapies." (PMID 36542699, 2022). "According to previous studies, EIF4B is an important translation regulator in cancer and can interact with lncRNA GMAN in HCC cells to promote its progression." (PMID 34765550, 2021). "Our results showed that eIF4B protein was regulated by STAT3 in a variety of cancer cells, and eIF4B downregulation itself had little effect on cap‐dependent translation." (PMID 32495998, 2020). "As it appears to be functionally relevant for spontaneous metastasis, EIF4B becomes even more interesting as an anti-cancer target." (PMID 30228356, 2018). "Despite extensive interest in the eIF4E, eIF4G and eIF4A components, few studies have addressed the function of eIF4A cofactors, namely eIF4H and eIF4B, in cancer progression." (PMID 26498689, 2015). "Additionally, ERK2 directly phosphorylated eIF4B at Ser93, while inhibiting this phosphorylation is essential for the anti-cancer efficacy of the ERK2 inhibitor, Vx-11e." (PMID 41490890, 2026). "Protein synthetic rates are significantly reduced following apoptosis induction, where caspase-dependent proteolytic cleavage and altered phosphorylation states of translation initiation factors (eIF4GI, eIF4GII, eIF4E, eIF4B, and eIF2α) influence cancer progression." (PMID 34526485, 2021). "This hypothesis was further supported by the finding that R2 cells lost the expression of EIF4B, a substrate of the mTOR pathway, required for cell proliferation and survival of cancer cells." (PMID 31013771, 2019). "Indeed, USP11 was noted to be phosphorylated by S6Kinase that increases its interaction with eIF4B and subsequently enhanced cancer-promoting gene translation." (PMID 29483509, 2018). "However, this redundant mechanism of eIF4B activation can be hijacked by cancer cells to evade pharmacological treatment and develop drug tolerance, thus resulting in short-lived single agent targeted tumor therapy." (PMID 26848623, 2016). "Altogether, studies of eIF4B and related translation initiation factors have shed light on the complexity of mammalian translational regulation, and indicated that these components represent potential targets for novel anti-cancer therapies." (PMID 26133373, 2015). "During tumor development and progression, hypoxia, acidosis, glucose depletion and a lack of other nutrients are caused by a combination of defective perfusion, abnormal tumor vasculature and uncontrolled proliferation of cancer cells, leading to eIF4B dephosphorylation." (PMID 26498689, 2015). "Furthermore, S6K1 modulation of eIF4B phosphorylation regulates the expression of the key transcription factor cMyc in cancer cells." (PMID 26453749, 2015). "In agreement with that, our present study revealed that EIF4B in CCA cells bound to the GGAA sequence of miR-30a-5p whose loading into CCA cell-derived exosomes was enhanced in the presence of EIF4B, which greatly induces cancer-associated angiogenesis and metastasis." (PMID 37781039, 2023).
cancer (continued). "In total, the identification of hypoxia-dependent RNA–protein complexes such as eif4b and map2k1 and their molecular characterization in cancer signaling should provide insight into new pathways that may modulate translation rates in resistant and hypoxic cancer cells." (PMID 29270287, 2017). "Previous studies demonstrated that MELK interacts with and phosphorylates its downstream substrates including FOXM1, eukaryotic translation initiation factor 4B (eIF4B) and SQSTM1, and thus promotes the malignant phenotype of human cancer." (PMID 32047721, 2020). "Collectively, the results indicate that eIF4B integrates the signals from Pim and PI3K/Akt/mTOR pathways in Abl-expressing leukemic cells, and is a promising therapeutic target for such cancers." (PMID 26848623, 2016). "On the other hand, the roles of eIF4B and SRSF1 in cancer have been widely elucidated." (PMID 35571614, 2022). "However, in cancer cells such as ACHN cells, in which eIF4B plays an important role, it is possible to stimulate cell growth by regulating cap‐dependent translation through the expression of eIF4B and mLST8 by STAT3." (PMID 32495998, 2020). "However, further studies are needed to determine the clinical significance of directly targeting eIF4B in CML patient samples and other cancers." (PMID 26848623, 2016).
tumor (28 papers, 2013 to 2025). "In addition to the two ILC subtypes that we characterized, we also found associations between molecular features of ILC and clinical outcome: based on the mutation rate and eIF4B level of the tumours, we were able to distinguish three subgroups with different prognosis." (PMID 26729235, 2016). "Further examination indicated that EIF4B knockdown inhibited angiogenesis, sprout and diminished tumor growth and lung metastasis in mice." (PMID 37781039, 2023). "For example, USP11 stabilizes eIF4B, which acts as a transcription factor to increase the mRNA translation of tumor proteins such as cMYC, BCL2, and BCL6, thereby promoting oncogenic translation." (PMID 35359344, 2022). "Other studies have experimentally validated that the EIF4B results in poor prognosis of tumor patients, increasing the credibility of our data." (PMID 36466711, 2022). "Together, these data strongly suggest that USP11 promotes DLBCL proliferation, in part by enhancing protein translation of eIF4B-dependent oncogenes and diminishing tumor-suppressor gene expression." (PMID 29483509, 2018). "Willis and colleagues, while studying the altered oncogenic protein translation in DLBCL patients, observed that enhanced activity of eIF4B alone was sufficient for tumor cell survival." (PMID 29483509, 2018). "In that report the translation initiation factor eIF-4B was identified among several genes transcriptionally down-regulated in the ASIP-expressing tumor cell cultures." (PMID 27028866, 2016). "The expression levels of IGF2BP2, RAI2, SLC25A27, NCBP2, and EIF4B were greatly enhanced, as is the case in tumor development." (PMID 25978455, 2015). "Consistently, anti-sense RNAs targeting eIF4E, eIF4A and eIF4B decreased the proliferation rate of tumor cells and their ability to grow in soft agar." (PMID 23776612, 2013). "A similar evidence was reported for eIF4B, the human paralogue of eIF4H, which promoted the tumour growth and increased the translation of mRNAs harbouring 5′UTR secondary structures, including oncogenes." (PMID 23776612, 2013). "We found a total of 16 RBPs that could match to lncRNA-n326322, including RBMY1A1, EIF4B, and Pum2, which have been reported to have an important influence on tumor progression." (PMID 29416735, 2018). "Overall, these data suggest that modifying eIF4B expression/activity alters the expression levels of tumor suppressors and may provide an anti-tumor effect in DLBCL." (PMID 29483509, 2018). "Furthermore, Western blotting analysis of tumor lysates showed that eIF4B Ser422 phosphorylation was more significantly reduced by the combined inhibition of Pim and mTOR as compared to the single inhibitions." (PMID 26848623, 2016). "Indeed, the synergic inhibition of tumor growth by the combined treatment was greatly compromised by the expression of eIF4B-S422E in K562 cells." (PMID 26848623, 2016). "Together, these data indicate that eIF4B functions downstream of STAT/Pim and PI3K/Akt/mTOR signaling in Abl transformants, and Ser422 phosphorylation is associated with synergic inhibitory effects on cell survival and tumor growth induced by combined blockage of Pim and PI3K/Akt/mTOR pathways." (PMID 26848623, 2016). "For example, binding of eIF4B to eIF4A1 enhances translation initiation, and we observe an increase of this interaction in DoHH-2 (tumour) relative to GM01953 (non-tumour)." (PMID 39225047, 2024). "The peptides with increased presentation in SK-Mel-28 dr cells derived from EIF4B, FAM20B, LDHB, CYCS, C5orf22, RCAN1 and DIEXF and were recurrently identified in TvHdb in a variety of tumor patients." (PMID 39835134, 2024). "CircRBMS3 knockdown in tumor tissues resulted in a significant overexpression of terminal dUTP nick end labeling (TUNEL)-positive cells, whereas the levels of Ki67, eIF4B or YRDC were decreased, while inhibition of miR-424 reversed these effects." (PMID 36897170, 2023).
tumor (continued). "In addition, the wound healing and transwell assays revealed the inhibition of eIF4B and YRDC reduced tumor cells migration and invasion." (PMID 36897170, 2023). "The expression of EIF4H at mRNA levels, but not EIF4B, was enhanced in the tumor tissue of patients with LUAD." (PMID 36101357, 2022). "The role of eif4b has not been thoroughly investigated until now, nor has the effect of tumor hypoxia on its expression and vice versa." (PMID 29270287, 2017). "EIF4B and YRDC are known as oncogenes in some tumor types, while their function in OS is currently not understood." (PMID 36897170, 2023). "This suggested that recovery of EIF4B and MELK phosphorylation represented a marker of proliferative tumor progression rather than a driver of resistance to AZD8055." (PMID 37642941, 2023).
infection (8 papers, 2017 to 2024). The state of being infected such as from the introduction of a foreign agent such as serum, vaccine, antigenic substance or organism. "In contrast, almost 100 transcripts related to genes typically involved in viral protein translation during infection (e.g. rps2, 12, 14; wdr12; rpf2; nip7; eif4; eif4ebp3l; eif4a3; eif4ea; eif4b) were down-regulated." (PMID 35710351, 2022). "Another helicase, eIF4B, showed similar levels within whole cell lysates at late times post infection but was reduced within m7GTP-purified complexes." (PMID 28087593, 2017). "Similarly, omission of eIF4B, a cofactor that stimulates eIF4A activity and was recently reported to bind flaviviral genomes during infection, reduced the efficiency of translation initiation (compare lanes 11 and 12)." (PMID 31392996, 2019). "Notably, the protective phenotypes when targeting EIF4E2 and EIF4H do not appear to reflect a general effect of perturbing translation factors, as EIF4B did not significantly alter infection dynamics." (PMID 37803001, 2023).
EIF4B also shares sentences with these, for which no sentence is quoted: adenoma (1 paper); astrocytomas (1); bacterial infection (1); clear cell carcinoma (1); colon adenocarcinoma (1); colorectal adenocarcinoma (1); COVID-19 (1); diabetic retinopathy (1); dyslipidemia (1); granulosa cell tumor (1); inflammation (1); Kaposi's sarcoma (1); liver cancer (1); lung carcinoma (1); meningioma (1); mucoepidermoid carcinoma (1); myocardial infarction (1); NUT carcinomas (1); oligodendroglioma (1); oral squamous cell carcinoma (1); osteosarcoma (1); ovarian carcinoma (1); pancreatic cancer (1); Parkinson disease (1); postherpetic neuralgia (1); prostate carcinoma (1); skin cancer (1); skin cutaneous melanoma (1); squamous cell carcinoma (1); thymoma (1).